REG4 (regenerating family member 4)
Diseases named in the same sentence as REG4 in open-access papers (continued):
Sharing a sentence is not in itself a finding about the gene and the disease.
prostate carcinoma (11 papers, 2012 to 2022). A carcinoma that arises from epithelial cells of the prostate gland. "In prostate cancer, 14 (14%) of 98 cases had tissues positive for REG4 staining, which was associated with MUC2 and chromogranin A expression." (PMID 36172286, 2022). "Within this family, REG4 has been reported to be associated with human gastrointestinal malignancies and prostate cancer." (PMID 23342005, 2013). "Further investigation of the correlation between ADAM9 and REG4 may help to understand the underlying mechanism of therapy-resistance in prostate cancer." (PMID 33489872, 2020). "The expression of REG4 was a significant prognostic factor and independent predictor of the relapse-free survival of patients with prostate cancer." (PMID 36172286, 2022). "In prostate cancer, the serum REG4 concentration was significantly higher in patients with prostate cancer than in control individuals." (PMID 36172286, 2022). "REG4 has been shown to be a prognostic factor in clinically localized prostate cancer and a promising marker of hormone refractory metastatic prostate cancer." (PMID 31303963, 2019). "Previous reports have shown that REG4 mRNA is strongly expressed in inflamed epithelium, dysplasia and cancerous lesions of ulcerative colitis, and REG4 overexpression has been observed in gastric, colorectal, pancreatic, hepatocellular and prostate cancers." (PMID 26077911, 2015). "Microarray data showed significantly decreased levels of regenerating islet-derived family member 4 (REG4) expression in prostate cancer cells with knockdown of ADAM9 gene expression." (PMID 23342005, 2013). "There are only two studies about the clinical role of REG4 in prostate cancer." (PMID 33489872, 2020). "Moreover, high expression of REG4 in prostate cancer correlated with tumor recurrence, metastasis and therapy failure." (PMID 33489872, 2020). "REG4 has been previously indicated as a serum biomarker in gastric, colorectal and prostate cancer." (PMID 26981633, 2016). "Knockdown of REG4 affects the ability of insulin and EGF to phosphorylate downstream tyrosine kinase in human colon and prostate cancer cells." (PMID 33489872, 2020). "Given that knockdown ADAM9 decreases the expression of REG4, we suggest a regulatory role of ADAM9 in REG4-mediated prostate cancer progression." (PMID 23342005, 2013). "Several lines of studies in other cancer types have demonstrated an impact of REG4 on tumor growth, invasion, metastasis, and resistance to apoptosis, which is similar to the role of ADAM9 in prostate cancer seen in the previous and the present studies." (PMID 23342005, 2013). "Although upregulated REG4 is frequently observed in CRPC and is considered to be a prognostic indicator of cancer relapse after radical prostatectomy, the biological function of REG4 in prostate cancer progression has only begun to be explored." (PMID 23342005, 2013).
inflammatory bowel disease (8 papers, 2012 to 2024). A spectrum of small and large bowel inflammatory diseases of unknown etiology. "For instance, REG4, a member of the small secretory protein family, was reported to participate in inflammatory bowel diseases and intestinal cancers." (PMID 35928108, 2022). "REG4 is expressed in various diseases or tumors, such as inflammatory bowel diseases and gastrointestinal malignancies." (PMID 34577861, 2021). "REG4 was originally identified by a high-throughput sequence analysis of a cDNA library derived from patients with inflammatory bowel disease." (PMID 33489872, 2020). "REG4 is expressed in parietal cells of the gastric mucosa and epithelial neuroendocrine cells of the small intestine, and inflammatory bowel disease." (PMID 33489872, 2020). "REG4, is expressed in inflammatory bowel diseases and also in the margins of peptic ulcers, is considered a marker of inflammation." (PMID 25295732, 2014). "In addition to being among the 21 most upregulated genes in inflammatory bowel disease (IBD), SPINK4 was the gene that most strongly co-expressed with REG4 in IBD." (PMID 38066386, 2024). "REG4 and SPINK4 have been shown top regulated genes in inflammatory bowel disease (IBD), but with no clear role in development of VTE." (PMID 38066386, 2024).
lymph node metastasis (8 papers, 2014 to 2022). "High REG4 expression was significantly associated with poor differentiation (p=0.004), lymph node metastasis(p=0.041), and advanced TNM stage(p=0.028), but was unrelated to other factors, such as, gender, age, tumor location, and T stage." (PMID 27036049, 2016). "REG4 expression was positively correlated with dedifferentiation, local invasiveness, and lymph node metastasis of gallbladder cancer." (PMID 36172286, 2022). "REG4 expression in CRC tissue was linked to distant and lymph-node metastasis and histologic grade." (PMID 35928108, 2022). "Moreover, REG4 expression showed a trend like association with low T-stage, absence of lymph node metastasis, and local disease (Dukes A-B vs C-D)." (PMID 25295732, 2014). "None of the patients’ REG4 negative tumors showed positivity in their lymph-node metastasis, whereas of the 5 patients with REG4-positive tumor, 2 showed positivity also in their lymph node metastasis." (PMID 25295732, 2014).
adenoma (7 papers, 2012 to 2025). A neoplasm arising from the epithelium. "REG4 expression was higher in borderline lesions and carcinoma than in adenoma, and in colloid carcinoma than that in tubular carcinoma, respectively, and positively correlated with CDX2 expression." (PMID 36172286, 2022). "Adenomas from 14-week-old APCmin/+ mice showed significantly up-regulated expression of Bcl-2 and REG4." (PMID 36172286, 2022). "REG4 mRNA levels were found to be significantly higher in adenoma than in the normal mucosa of the colon." (PMID 34577861, 2021). "In adenomas, REG4+ DCS cells were enriched alongside OLFM4+ CSCs, suggesting that tDCS cells may provide trophic support to OLFM4+ stem-like populations." (PMID 41282138, 2025). "Marked increased expression of MUC17, the cell junction protein genes VSIG1 and GJB5, and the antiapoptotic gene REG4 were found in SSA/Ps, relative to controls and adenomas, were verified by qPCR analysis of additional SSA/Ps (n = 21) and adenomas (n = 10)." (PMID 24533081, 2014). "REG4 mRNA was found to be highly expressed in all adenoma samples, with or without concurrent colorectal carcinoma, compared to normal mucosa samples." (PMID 36172286, 2022).
mucinous carcinomas (6 papers, 2015 to 2024). "Our results indicate that mucinous adenocarcinoma cancer cells have goblet cell-like properties, and express high levels of goblet cell markers (REG4, SPINK4, FCGBP and MUC2) compared to classical adenocarcinoma cancer cells." (PMID 36690709, 2023). "Concurring with the previous analyses, no staining was detected in serous (n = 90) or endometrioid neoplasms (n = 45), while positive REG4 staining was found in 83% (30/36) of mucinous carcinomas." (PMID 26981633, 2016). "Higher REG4 mRNA expression was observed in mucinous carcinomas than serous carcinomas (P < 0.05), and in well- and moderately-differentiated carcinomas than poorly-differentiated carcinomas (P < 0.05)." (PMID 26077911, 2015). "In ovarian carcinogenesis, REG4 mRNA and protein levels were higher in ovarian tumors than in normal ovaries, in mucinous carcinomas than in serous carcinomas, and in well- and moderately-differentiated carcinomas than in poorly-differentiated carcinomas, respectively, in line with another report." (PMID 36172286, 2022). "REG4 protein expression was significantly higher in ovarian mucinous borderline tumors and mucinous carcinomas than in mucinous cystadenomas, and was more closely associated with ovarian borderline, intestinal-type, mucinous tumors rather than in endocervical-like type tumors." (PMID 36172286, 2022). "Strong REG4 staining was detected equally in low and high grade mucinous carcinomas." (PMID 26981633, 2016). "In addition, mucinous carcinomas showed higher REG4 expression than serous ones (P < 0.05)." (PMID 26077911, 2015). "In order to determine the correlation of REG4, CA125 and HE4 concentrations to tumor burden, serum samples were measured at multiple time points from a patient (M1) treated for disseminated mucinous carcinoma (see S4 Table for detailed results)." (PMID 26981633, 2016). "The REG4 mRNA showed high overall expression in mucinous carcinomas (MUC_C_4–10) while no expression was detected in high-grade serous tumors (SER_1–3)." (PMID 26981633, 2016). "The gastrointestinal oncogenic REG4 signature is shared from both NOS (not otherwise specified) and mucinous adenocarcinoma." (PMID 39632825, 2024).
ovarian carcinoma (6 papers, 2008 to 2022). A malignant neoplasm originating from the surface ovarian epithelium. "High REG4 mRNA expression was inversely associated with inferior overall, progression-free and post-progression survival in patients with ovarian cancer receiving platinum chemotherapy." (PMID 36172286, 2022). "Taken together, these results suggest that REG4 overexpression is closely linked to the pathogenesis of ovarian mucinous carcinoma and differentiation of ovarian cancer." (PMID 26077911, 2015). "Furthermore, REG4 expression was closely linked with mucinous tumors, differentiation and adverse prognosis of ovarian cancer." (PMID 26077911, 2015). "Our findings indicate that aberrant REG4 expression plays an essential role in early ovarian carcinogenesis and is closely linked to mucinous ovarian tumors, differentiation and adverse prognosis of ovarian cancer by modulating proliferation, apoptosis, migration and invasion." (PMID 26077911, 2015). "In ovarian cancer cells, REG4 expression or 5-FU chemoresistance was enhanced by CDX2 transfection, in contrast to CDX2 knockdown." (PMID 36172286, 2022). "As an independent factor, the expression of REG4 was an overall or relapse-free poor prognostic factor for patients with ovarian cancer." (PMID 36172286, 2022). "Here we suggest REG4 as a promising serum biomarker for separating mucinous cancers from other epithelial ovarian cancer subtypes." (PMID 26981633, 2016). "A recent study suggests that REG4 modulates proliferation, apoptosis, migration and invasion of ovarian cancer cells, and has an important role in early ovarian carcinogenesis." (PMID 26981633, 2016). "This study also reports immunohistochemical staining of REG4 from different ovarian cancer subtypes." (PMID 26981633, 2016). "To assess the specificity of REG4 for mucinous ovarian cancer histotype, we analyzed CA125, HE4 and REG4 concentrations from preoperative serum samples of ovarian cancer patients with high-grade serous (n = 4) or mucinous (n = 3) cancers." (PMID 26981633, 2016). "In accordance with previous reports on gliomas and CRC, we found an inverse relationship between REG4 expression and cumulative or relapse-free survival rate of patients with ovarian cancer." (PMID 26077911, 2015). "Survival analysis revealed an inverse relationship between REG4 expression and cumulative or relapse-free survival rates of the patients with ovarian cancer as an independent factor (P < 0.05)." (PMID 26077911, 2015). "Here, we investigated the effect of REG4 overexpression and recombinant REG4 on the proliferation, apoptosis, invasion and migration of ovarian cancer cell lines, and explored the related mechanisms." (PMID 26077911, 2015). "We found that REG4 mRNA and protein expression levels in ovarian cancer were significantly higher in mucinous tumors than in serous tumors, and were positively associated with differentiation." (PMID 26077911, 2015). "Overexpression of REG4 protein increased the aggressiveness of ovarian cancer, as indicated by reduced apoptosis and increased proliferation, migration and invasion." (PMID 26077911, 2015). "Taken together, our findings suggest that REG4 represents an independent indicator of poor prognosis in ovarian cancer." (PMID 26077911, 2015). "Either REG4 overexpression or rhREG4 treatment promoted proliferation, G2/S progression, anti-apoptosis, migration, invasion, and cisplatin and paclitaxel resistance in ovarian cancer cells." (PMID 36172286, 2022). "In other ovarian cancer histotypes, REG4 mRNA expression remained at the level of healthy tissues." (PMID 26981633, 2016). "REG4 overexpression and treatment with recombinant REG4 both inhibited apoptosis, and enhanced G2/S progression, cell proliferation, migration and invasion in SKOV3 ovarian cancer cells." (PMID 33489872, 2020).
ovarian carcinoma (continued). "Our multivariate model indicates that REG4 expression, FIGO staging and differentiation are independent prognostic factors of overall survival in the patients with ovarian cancer." (PMID 26077911, 2015). "In addition, we examined REG4 expression in normal ovarian tissue, benign and borderline ovarian tumors, and primary and metastatic cancers, and compared our findings with the clinicopathological and prognostic parameters of tumors surgically resected from the patients with ovarian cancer." (PMID 26077911, 2015). "Serum REG4 values were not quantified in any ovarian cancer subtypes." (PMID 26981633, 2016). "The function of REG4 in ovarian cancer is poorly understood and has not been widely investigated." (PMID 26981633, 2016). "Our study suggests that combining REG4 with CA125 and HE4 could provide added value for preoperative diagnostics of ovarian masses of potential neoplastic origin, and enable distinction of mucinous ovarian cancer from other ovarian cancer subtypes with non-invasive methods." (PMID 26981633, 2016). "Thus, a combination of REG4 with CA125 and HE4 could provide a more comprehensive marker panel for preoperative diagnosis of potentially neoplastic ovarian masses, and enable distinction of mucinous ovarian cancer from other ovarian cancer histotypes." (PMID 26981633, 2016).
ulcerative colitis (6 papers, 2015 to 2024). An inflammatory bowel disease involving the mucosal surface of the large intestine and rectum. "Reg4 protein, encoded by a member of the regenerating (Reg) multigene family is a secretory islet-derived protein involved in growth and differentiation of cells, originally discovered through a high throughput assay of an ulcerative colitis library." (PMID 33659040, 2021). "REG4 (regenerated islet derived 4 gene), identified through high-throughput sequencing of ulcerative colitis cDNA library, binds to and kills inflammatory Escherichia coli by activating epidermal growth factor receptor (EGFR) /Akt/cAMP response elements." (PMID 38426148, 2024). "Regenerating islet-derived 4 (REG4) gene was discovered by high-throughput sequencing of ulcerative colitis cDNA libraries." (PMID 36172286, 2022). "REG4 was discovered by high-throughput sequencing of a cDNA library from an ulcerative colitis (UC) sample in 2001." (PMID 36172286, 2022). "Reg4 is a secretory islet-derived protein involved in growth and differentiation originally discovered through a high throughput assay of an ulcerative colitis library." (PMID 33659040, 2021). "A recent study investigating the link between REG genes and IBD reported that REG1A, REG1B, and REG4 are overexpressed in the colon of Crohn’s disease patients, and that REG4 is overexpressed in the colon of ulcerative colitis patients." (PMID 29807746, 2018).
chronic pancreatitis (4 papers, 2020 to 2024). A chronic inflammatory process causing damage and fibrosis of the pancreatic parenchyma. "In chronic pancreatitis, Reg4 deficiency aggravates inflammation and fibrosis and inhibits compensatory cell proliferation." (PMID 38769308, 2024). "In chronic pancreatitis (CP), Reg4 deletion aggravated pancreatic fibrosis and enhanced activation of the C-X-C motif ligand 12 (CXCL12)/C-X-C motif receptor 4 (CXCR4) axis." (PMID 38769308, 2024). "In addition, serum REG4 levels may be useful for differentiating between pancreatic ductal adenocarcinoma and chronic pancreatitis." (PMID 34577861, 2021). "A 2018 revealed that REG4 was not independent prognostic factor by multivariate analysis, although serum REG4 levels could be used in the differential diagnosis of pancreatic malignant cancers and chronic pancreatitis." (PMID 33489872, 2020).
colorectal adenoma (4 papers, 2012 to 2024). An adenoma that arises from the colon or rectum. "Combining these results, we conclude that up-regulated REG4 mRNA expression is markedly observed in colorectal adenoma and adenocarcinoma." (PMID 36172286, 2022).
gallbladder carcinoma (4 papers, 2012 to 2022). "REG4 expression was independently associated with a poor prognosis in patients with advanced gallbladder cancer." (PMID 36172286, 2022). "Similar results appear for gallbladder cancer, where positive REG4 IHC expression, associates with higher tumor differention." (PMID 25295732, 2014). "In gallbladder cancer, REG4 IHC expression has been associated with better prognosis." (PMID 25295732, 2014). "A high serum REG4 level was evident preoperatively in four (33%) of 12 patients with gallbladder cancer, but not in benign diseases, and was postoperatively reduced." (PMID 36172286, 2022).
mucinous cystadenoma (4 papers, 2011 to 2016). A benign or low malignant potential cystic epithelial neoplasm composed of cells which contain intracytoplasmic mucin. "Interestingly, REG4 was not expressed in mucinous cystadenoma (MUC_A_1) and showed significantly lower mRNA expression levels also in mucinous borderline tumors (MUC_B_2–3)." (PMID 26981633, 2016). "REG4 expression is constitutively high in mucinous tumors (i.e. Pseudomyxoma peritonei, and mucinous cystadenomas and mucocellular gastric cancer) This may explain why no clear variation in REG4 expression was found by IHC in the group of mucinous CRC tumours." (PMID 25295732, 2014). "Interestingly, no REG4 expression was detected in mucinous cystadenomas suggesting that immunohistochemical REG4 analysis could be used as an additional method for distinction between benign and malignant mucinous ovarian tumors." (PMID 26981633, 2016).